FCN2 (ficolin 2)
Diseases named in the same sentence as FCN2 in open-access papers (continued):
Sharing a sentence is not in itself a finding about the gene and the disease.
Stroke (4 papers, 2011 to 2022). Sudden impairment of blood flow to a part of the brain due to occlusion or rupture of an artery to the brain. "Only on the seventh day after the stroke differences were found regarding Bf, ApoA1, Fn, fetuin A, TrpRS and ficolin-2." (PMID 35054033, 2022). "As compared to healthy subjects, ficolin-2 plasma levels were significantly lower in stroke patient samples obtained within 6 h after the onset of symptoms." (PMID 26792363, 2016). "Compared to both healthy controls and patient controls, both ficolin-2 ficolin-3 levels were significantly lower both in the admission and follow-up sera of stroke patients." (PMID 22206485, 2011). "Concentrations of ficolin-2 and ficolin-3 were even higher in patient controls than in healthy subjects, indicating that the decreased levels in sera during the acute phase of stroke are related to the acute ischemic event." (PMID 22206485, 2011). "The differences observed between stroke patients and healthy individuals seem to be valid, since the ficolin-2 and ficolin-3 concentrations measured in the sera of healthy subjects are similar to previously reported data." (PMID 22206485, 2011). "In addition, ficolin-2 and ficolin-3 levels were significantly lower in sera of patients with definite stroke compared to patients with severe carotid atherosclerosis without clinical event as well." (PMID 22206485, 2011). "On the 7th day after the stroke, differences were found between the study group and the control group (group B vs. C) regarding complement factor B (Bf), apolipoprotein A-I (ApoA1), fetuin A, fibronectin (Fn), cytoplasmic tryptophanyl-tRNA synthetase (TrpRS) and ficolin-2." (PMID 35054033, 2022).
atherosclerosis (3 papers, 2011 to 2023). A disease characterized by the build-up of fatty material and calcium deposition in the arterial wall resulting in partial or complete occlusion of the arterial lumen. "The missing link between the genetic variants determining PTX3 and ficolin-2 levels with the risk of MI suggests that they act as markers of active atherosclerosis and complement activity rather than causal factors." (PMID 28216633, 2017). "We propose a novel mechanism whereby ficolin-2 contributes to the progression of atherosclerosis independent of complement activation by enhancing inflammation in the cross-talk between the smooth muscle cells and macrophages, key cells in the evolution of atherosclerosis." (PMID 37940674, 2023).
COVID-19 (3 papers, 2022 to 2025). A disease caused by infection with severe acute respiratory syndrome coronavirus 2. "The increase in Ficolin-2 that we show suggests, at least in children, that complement activation may be induced through the lectin pathway, which has been discussed in severe COVID-19 in adults." (PMID 35501302, 2022).
hepatitis B infection (3 papers, 2011 to 2024). "SNPs in FCN2 have also been implicated in viral infections, participating in the pathophysiology of hepatitis B infection." (PMID 30868077, 2019). "The very first study on Vietnamese cohort associates both Ficolin-2 serum levels and FCN2 haplotypes to hepatitis B virus infection and subsequent disease progression." (PMID 22140517, 2011). "Our results demonstrated that Ficolin-2 serum levels were found in higher patients with acute hepatitis B. During an acute stage, both innate and adaptive immunity are activated leading to increased production of cytokines and chemokines by cytotoxic T lymphocytes resulting in liver injury." (PMID 22140517, 2011). "Distribution of FCN2 haplotypes (-986/-602/-4/+6424) in hepatitis B patients and controls." (PMID 22140517, 2011). "Ficolin-2 and MBL also play a role in the pathogenesis of hepatitis B infection." (PMID 39057781, 2024).
idiopathic pulmonary fibrosis (3 papers, 2019 to 2023). Idiopathic pulmonary fibrosis (IPF) is a nonneoplastic pulmonary disease that is characterized by the formation of scar tissue within the lungs in the absence of any known cause. "In patients with idiopathic pulmonary fibrosis, above threshold levels of plasma FCN-2 were even associated with prolonged progression-free survival." (PMID 30885245, 2019). "This study investigated the role of mannose-binding lectin (MBL), ficolin-2 and ficolin-3 in ILD patients with a focus on idiopathic pulmonary fibrosis (IPF) and sarcoidosis." (PMID 33101280, 2020).
ischemic stroke (3 papers, 2011 to 2022). A stroke disorder caused by obstruction of blood flow to the brain, due to thrombotic (local blood clot formation) or embolic (due to a blood clot or other material traveling from another site) event. "On the 7th day after the onset of ischemic stroke symptoms, our study also showed an increased concentration of ficolin-2." (PMID 35054033, 2022). "Concentrations of both ficolin-2 and ficolin-3 were significantly (p < 0.001) decreased in both the admission and in the follow-up samples of patients with definite ischemic stroke as compared to healthy subjects." (PMID 22206485, 2011). "Therefore, we measured the levels of ficolin-2 and ficolin-3 in sera from 65 patients with ischemic stroke and from controls." (PMID 22206485, 2011). "For the first time, differential expressions of apolipoprotein B, apolipoprotein C-I, lipopolysaccharide-binding protein, vascular cell adhesion molecule 1, fibulin-1, and ficolin-2 were confirmed as being significantly upregulated in CAD as compared to non-CAD ischemic stroke subjects." (PMID 32508734, 2020). "Six candidate proteins (LBP, VCAM1, FCN2, FBLN1, APOC-I, and APOB) were assessed using individual samples from the CAD and non-CAD ischemic stroke subjects." (PMID 32508734, 2020).
liver cancer (3 papers, 2022 to 2023). An epithelial or non-epithelial malignant neoplasm that arises from the liver. "To further verify the association between FCN2 and liver cancer, we analyzed the expression of the FCN2 gene in several markers using the R tool." (PMID 36425563, 2022). "Based on this, this paper discusses the influence of the FCN2 gene on liver cancer and expects to expand the research in the future, more fully analyze the association between this gene and liver cancer, and apply gene therapy to better treat liver cancer." (PMID 36425563, 2022). "Because these immune-related associations are so significant, FCN2 may be developed as an immune checkpoint inhibitor for liver cancer." (PMID 36425563, 2022). "Ficolin-2 promoter polymorphism is associated with ficolin-2 concentrations, the AGGG haplotype contributes to the prevention of HBV infection and liver cancer, and AAAG is associated with higher serum ficolin-2 levels." (PMID 37424786, 2023). "To determine the link between the FCN2 gene and liver cancer, we used the R package to analyze the FCN2 gene expression in multiple indicators." (PMID 36425563, 2022). "This study found that FCN2 appears to play a role in the development and progression of liver cancer." (PMID 36425563, 2022). "FCN2 expression was shown to be lower in liver cancer tissues than in healthy liver tissues, which is consistent with our other findings." (PMID 36425563, 2022). "The results showed that, in contrast to normal tissues, the mRNA expression of FCN2 is downregulated in leukemia and liver cancer, demonstrating that the transcription of FCN2 is tumor-specific." (PMID 36425563, 2022). "The findings revealed that the mRNA and protein expressions of FCN2 were lower in liver cancer tissues than those in normal liver tissues in all cases (p < 0.05)." (PMID 36425563, 2022). "The expression of FCN2 mRNA in liver cancer tissues was similarly shown to be lower than that in normal liver tissues." (PMID 36425563, 2022). "The transcription and translation results of FCN2 mRNA in 369 liver cancer and 50 normal liver tissues were acquired using the GEPIA2 database." (PMID 36425563, 2022). "An Oncomine database search of the expression of FCN2 in diverse liver cancer studies produced three studies showing a lower expression of FCN2 in LIHC tissues compared to normal liver tissues (p = 1E−4, multiple of difference: 2)." (PMID 36425563, 2022). "We further analyzed the Clinical Proteomic Tumor Analysis Consortium (CPTAC) database and discovered that the FCN2 protein expression in liver cancer tissues was inferior to that in normal liver tissues." (PMID 36425563, 2022). "We used the Oncomine database to examine the expression of FCN2 mRNA in malignant tumors and normal clinical tissues in order to determine whether FCN2 has a specific expression in liver cancer." (PMID 36425563, 2022). "Downregulation of the gene expression of FCN2 was found in leukemia and liver cancer." (PMID 36425563, 2022). "Based on this assumption, we believe that FCN2 could be used as a biomarker in the early stages of liver cancer, but more research into the subject is required." (PMID 36425563, 2022). "Combining these methods, we have concluded that FCN2 could be an immune checkpoint inhibitor for liver cancer, which we hope will provide a breakthrough point in the cure of liver cancer." (PMID 36425563, 2022). "Previous studies have mostly focused on the aberrant expression of FCN2 in liver cancer." (PMID 36425563, 2022). "The mRNA expression levels of FCN2 in liver cancer tissues were lower than those in normal liver tissues, showing that FCN2 may play the role of a tumor marker in the occurrence and progression of liver cancer." (PMID 36425563, 2022). "It is hoped that by analyzing the mechanism and characteristics of FCN2 in the development of HCC, this study can provide useful information for the future of liver cancer." (PMID 36425563, 2022).
liver cancer (continued). "The expression of FCN2 was negatively correlated with the M1 macrophage biomarker (IRF5), neutrophil biomarker (ITGAM), and DC biomarker (ITGAX) in liver cancer." (PMID 36425563, 2022). "However, there is still potential for improvement in our research because the precise involvement of the FCN2 gene in the onset and progression of liver cancer, as well as its mechanism of impact, remains unclear, and many hypotheses must be confirmed by clinical data." (PMID 36425563, 2022). "This indicates that FCN2 has certain clinical importance, whether from the high and low FCN2 expression groups (median) or the expression analysis of normal liver tissue and different liver cancer subgroups, and could be a complementary gene for AFP detection in liver cancer." (PMID 36425563, 2022).
liver fibrosis (3 papers, 2022 to 2025). "It has been found that plasma FCN2 expression was decreased in patients with pathological obesity and negatively correlated with the stage of liver fibrosis in patients with non-alcoholic fatty liver disease." (PMID 39609876, 2024). "In the present study, we assessed the performance of Ficolin-2 protein (FCN-2) as a putative novel biomarker of liver fibrosis and tested its utility combined in a blood-based score test." (PMID 35269955, 2022). "FCN2 has not specifically been linked to kidney fibrosis but lower levels predicted more severe liver fibrosis in people with non-alcoholic fatty liver disease." (PMID 40342947, 2025). "Our data agreed with those reported by Dai where FCN-2 and CPB2 proteins were shown as biomarkers of liver fibrosis through serum proteomics analysis and quantified using ELISA in a cohort of 46 CHB subjects." (PMID 35269955, 2022).
Obesity (3 papers, 2024). Accumulation of substantial excess body fat. "With high statistical significance, proteins FABP4, FCN2, and LEP showed 2-fold, 2.6-fold, and 4-fold increases in expression in the group of individuals with obesity, respectively." (PMID 38732002, 2024).
ovarian carcinoma (3 papers, 2013 to 2022). A malignant neoplasm originating from the surface ovarian epithelium. "We later found elevated serum Ficolin-2 (L-ficolin) and Ficolin-3 (H-ficolin) in ovarian cancer patients, while the local expression of the corresponding genes was decreased." (PMID 25038892, 2014).
preeclampsia (3 papers, 2017 to 2019). Preeclampsia is a hypertensive disorder of pregnancy that is characterized by new-onset hypertension with proteinuria presenting after 20 weeks of gestation, and depending on mild or severe forms may initially present with severe headache, visual disturbances, and hyperreflexia. "Women with preeclampsia showed an association between plasma ficolin-2 concentrations and placental growth factor (PIGF) concentrations and an inverse association with serum levels of soluble fms-like tyrosine kinase-1 (sFlt-1)." (PMID 32010144, 2019). "Of note, discriminating early preeclampsia from both normal pregnancy and late preeclampsia cases involved more stringent cut-offs for the same proteins and also new proteins such as ficolin 2 (FCN2)." (PMID 31163045, 2019). "The decrease in ficolin-2 may therefore contribute to the development of endothelial dysfunction and the maternal features preeclampsia." (PMID 32010144, 2019).
respiratory infections (3 papers, 2013 to 2023). "Although clinical research involving FCN2 is still in its infancy, evidence is emerging that suggests insufficiency of FCN2 may increase susceptibility to respiratory infections." (PMID 32508734, 2020). "A prospective study found that serum ficolin-2 concentrations were significantly lower in patients with allergic airway disease and respiratory infections." (PMID 37996869, 2023). "The authors proposed that decreased ficolin-2 levels could make individuals more vulnerable to respiratory infections, which could result in allergic diseases." (PMID 37996869, 2023).
rheumatoid arthritis (3 papers, 2022 to 2025). A chronic, systemic autoimmune disorder characterized by inflammation in the synovial membranes and articular surfaces. "A systematic literature review was performed using the following keywords “gene (FCN1/FCN2/FCN3)”, “Polymorphism/Genetic Variant”, and “rheumatoid arthritis” in different databases until January 2022." (PMID 36569030, 2022). "The present systematic review was conducted to synthesize the results of the studies in order to establish the impact of polymorphisms in the ficolin-coding genes FCN1, FCN2, and FCN3 on the susceptibility to develop rheumatoid arthritis." (PMID 36569030, 2022). "The FCN1 gene variants, particularly rs2989727 and rs1071583, have been reported to be linked to increased risk of developing rheumatoid arthritis in Brazilian and Belgian populations, whereas no such associations were observed for FCN2 or FCN3 variants." (PMID 41285030, 2025). "The FCN1 gene variants rs2989727 and rs1071583 are associated with the risk of developing rheumatoid arthritis in populations from Brazil and Belgium, but not in FCN2 and FCN3 gene variants." (PMID 36569030, 2022). "Previous study has reported an elevated serum FCN2 concentration in patients with Rheumatoid arthritis (RA), where the elevated serum FCN2 level showed positive correlation with swollen joint counts (SJCs) and rheumatoid factor (RF)." (PMID 38750493, 2024). "Both polymorphisms in the FCN1 gene (rs2989727 and rs1071583), but not in FCN2 and FCN3, are associated with the risk of developing rheumatoid arthritis in populations from Brazil and Belgium." (PMID 36569030, 2022).
asthma (2 papers, 2023 to 2025). "In addition, our group has previously shown changes associated with asthma in the serum levels of many of the proteins detected in urine, i.e., IGFALS, FCN2, HSPG2, CD26/DPP4, and CD14, and suggested their use as potential phenotype/severity biomarkers of this disease." (PMID 39858454, 2025).
autoimmune disease (2 papers, 2024 to 2025). A disorder resulting from loss of function or tissue destruction of an organ or multiple organs, arising from humoral or cellular immune responses of the individual to their own tissue constituents. "While higher titers of FCN2 indicates its role in autoimmune diseases, more in-depth studies are necessary to elucidate the underlying mechanisms." (PMID 38750493, 2024). "Emerging evidence suggests that FCN2 plays a significant role in the onset and progression of autoimmune diseases." (PMID 38750493, 2024). "Ficolins have been confirmed as crucial contributors to autoimmune diseases, with Ficolin-2 being particularly elevated in patients with autoimmune diseases." (PMID 38750493, 2024).
Behcet disease (2 papers, 2015 to 2022). A chronic, relapsing, multisystemic vasculitis characterized by mucocutaneous lesions, as well as articular, vascular, ocular and central nervous system manifestations. "However, no such findings were observed in patients with Behcet's disease, indicating that FCN2 polymorphisms vary with different diseases." (PMID 26379154, 2015).
benign ovarian tumors (2 papers, 2013 to 2022). "In contrast to serum concentrations, the expression of FCN2 gene (reported for the first time in ovarian sections) was significantly lower in women with OC in comparison with patients with NO but not with benign ovarian tumours." (PMID 23744477, 2013).
carotid atherosclerosis (2 papers, 2011 to 2017). A thickening and loss of elasticity of the walls of carotid arteries that occur with formation of atherosclerotic plaques. "Füst and collaborators showed increased ficolin-2 and ficolin-3 serum levels in asymptomatic patients with severe carotid atherosclerosis compared to healthy controls or to patients after acute stroke." (PMID 28360913, 2017).
Chagas disease (2 papers, 2013 to 2015). A parasitic infection caused by Trypanosoma cruzi. "The very first study on Brazilian cohort associates both L-ficolin plasma levels and FCN2 variants to Chagas disease and subsequent disease progression." (PMID 23593180, 2013). "The role of ficolin-2, as an innate immunity component, has been studied in several infectious diseases including Hepatitis B, schistosomiasis, Chagas disease and others." (PMID 25965808, 2015).
diabetes (2 papers, 2015 to 2018). "Another member of the ficolin family; ficolin-3 (FCN3), which shares approximately 50% amino acid sequence homology with FCN2, is also associated with insulin resistance and diabetes." (PMID 30618716, 2018).
glomerular disease (2 papers, 2021 to 2025). "FCN2 could be involved in fibrosis by complement activation, associated to myofibroblast activation and fibrogenesis in various animal models of glomerulopathies and FSGS47,48." (PMID 34675284, 2021).
inflammatory bowel disease (2 papers, 2024 to 2025). A spectrum of small and large bowel inflammatory diseases of unknown etiology. "Similarly, higher titers of FCN2 were also found in Crohn’s disease (CD), a form of inflammatory bowel disease (IBD)." (PMID 38750493, 2024).
kidney failure (2 papers, 2021 to 2025). An acute or chronic condition that is characterized by the inability of the kidneys to adequately filter the blood. "Sequencing of the genes for MBL and L-ficolin, MBL2 and FCN2, identified association between future kidney failure and the MBL2 variant rs1800450-A in IgAN." (PMID 34379175, 2021). "In that study, high FCN1 levels predicted development of kidney failure, defined as recorded initiation of KRT in the Danish Renal Registry, but FCN2 did not." (PMID 40342947, 2025).